NOTCH1 (notch receptor 1)
Diseases named in the same sentence as NOTCH1 in open-access papers (continued):
Sharing a sentence is not in itself a finding about the gene and the disease.
squamous cell carcinoma (53 papers, 2010 to 2026). A carcinoma arising from squamous epithelial cells. "The Notch pathway is known to play a key role in squamous differentiation, and inactivating mutations in NOTCH1 were frequently observed in squamous cell carcinomas." (PMID 37444412, 2023). "In this study, TMB-high status was more common in squamous cell carcinoma, as well as in tumors harboring mutations in NOTCH1, FGFR3, or FGFR4." (PMID 34860358, 2022). "In the head and neck, a large proportion of squamous cell carcinoma demonstrate a mutation of the NOTCH1 gene." (PMID 35205828, 2022). "This is particularly evident in various forms of squamous cell carcinomas, where, for example, 70–80% of skin squamous cell carcinoma tumors exhibit loss-of-function NOTCH1 or NOTCH2 mutations." (PMID 35682918, 2022). "Mutations of Notch1, for instance, have been identified in squamous cell carcinoma of the head and neck, esophagus and skin and have been linked with a hypoactivation of the pathway." (PMID 32796631, 2020). "Inactivating mutations of Notch1 can be found in approximately 10% of all cases of squamous cell carcinoma including the oral cavity, indicating that Notch1 is one of the most mutated gene in squamous cell carcinoma." (PMID 30917608, 2019). "Conversely, loss-of-function mutations distributed over a large part of the NOTCH1 locus are common in squamous cell carcinomas of the skin and head and neck and also occur in a smaller subset of squamous cell carcinomas of the lung." (PMID 23825651, 2013). "To answer this question, we ran an immunohistochemical study of Notch1 and Hes-1 in a series of human squamous cell carcinomas collected in a high-risk area in China." (PMID 23409141, 2013). "In clinical samples, Notch1 protein expression was detected in the basal cells of human esophagus epithelia, and its expression in squamous cell carcinomas was significantly associated with higher pathological grade and shorter overall survival." (PMID 23409141, 2013). "The NOTCH1 gene, frequently implicated in squamous carcinomas, was also mutated in P1." (PMID 40486961, 2025). "Interestingly, ERβ also directly controls NOTCH1 gene expression during differentiation through RNA polymerase II pause release, while mutations in NOTCH1 are associated with the development of squamous cell carcinoma (SCC)." (PMID 38672656, 2024). "Because NOTCH1 loss-of-function mutations are common in other squamous cell carcinomas, including those of the esophagus and lung, our findings may translate beyond HNSCC." (PMID 36124629, 2022). "It has also been reported that Notch may function as tumor suppressor in squamous cell carcinomas (SCCs) of cutaneous, lung, head and neck and esophageal where Notch1 mutations are associated with Notch1 loss of function." (PMID 28036048, 2016). "Staining for NICD1 may also prove useful in identifying tumors with NOTCH1 loss-of-function mutations, which are present in a subset of squamous cell carcinomas." (PMID 23825651, 2013).
squamous cell carcinoma (continued). "Interestingly, high rates (71%) of NOTCH-1 mutations have been shown in a whole-exome sequencing study of squamous cell carcinomas of the penis, a male tumor with many similarities with VSCC (dual HPV-associated/HPV-independent pathway, similar precursor lesions)." (PMID 34209172, 2021). "While direct evidence linking NOTCH1 to PD-L1 regulation in squamous cell carcinoma remains limited – and the relationship is complex and context-dependent – research indicates that NOTCH1 plays a multifaceted role in this cancer type." (PMID 41488620, 2025). "For some other cancers such as squamous cell carcinoma and SCLC, NOTCH functions as a tumor suppressor, as indicated by recurrent loss-of-function NOTCH1 gene mutations." (PMID 39024561, 2024). "For example, in squamous cell carcinoma RND3 seems to mediate the translocation of the intracellular domain of NOTCH1 to the nucleus and its binding to the promoter of its target genes." (PMID 38343633, 2024). "Overexpression of NOTCH1 was also reported in other squamous cell carcinomas such as HNSCC, cutaneous SCC and oral SCC." (PMID 37444412, 2023). "In summary, the action of NOTCH1 in the development of squamous cell carcinomas, its role as both a tumor suppressor gene and as a protooncogene, is not yet fully understood." (PMID 37008245, 2023). "LOXL2 directly interacts with the NOTCH1 promoter to suppress NOTCH1 expression in squamous cell carcinoma (SCC), contributing to tissue homeostasis." (PMID 36232685, 2022). "Since this seminal discovery in 2004, mutations, deletions and amplifications (indels) of NOTCH receptors, mainly of NOTCH1, have been identified in most or all epithelial cancers, including breast adenocarcinoma and various squamous cell carcinomas." (PMID 34944837, 2021). "In HNSCC, Notch1 expression is significantly increased and correlates with the advanced stages of squamous cell carcinoma, as determined by a microarray and qRT-PCR analysis." (PMID 32796631, 2020). "Sun-exposed skin can lead to an invasive squamous cell carcinoma, where Notch1 is downregulated, whereas sun-protected sites showed physiological normal expression." (PMID 32796631, 2020). "In squamous cell carcinomas, Notch1-induced RhoE activation is essential for nuclear translocation of NICD." (PMID 31057403, 2019). "The expression of NOTCH 1 receptor gradually increased during the progression from cervical intraepithelial neoplasia to squamous cell carcinoma of the cervix, demonstrating that NOTCH 1 was highly expressed in the tissues of cervical cancer." (PMID 31205475, 2019). "The clinical impact of the expression of NOTCH1 signaling components in squamous cell carcinoma of the pharynx and larynx has only been evaluated in subgroups." (PMID 29533972, 2018). "Notch1 and other Notch receptor paralogs cooperate to act as a tumor suppressor in squamous cell carcinomas (SCCs)." (PMID 29170450, 2017). "The tumor-suppressive role for NOTCH1 in squamous cells is also supported by recent sequencing studies of related tumor types, such as squamous cell carcinomas of the head and neck, skin, and lung." (PMID 26528858, 2016). "A recent study showed that higher NOTCH1 was expressed in 44% of adenocarcinomas (n = 113), 35% of large cell carcinomas (n = 31), and 26% of squamous cell carcinomas (n = 191)." (PMID 26491213, 2015). "Since the signaling pathways mediated by STAT3, Notch1 and Wnt2 play beneficial roles in CC formation and progression, the effects of resveratrol on them in cervical adenocarcinoma (HeLa) and squamous cell carcinoma (SiHa) cells were analyzed." (PMID 25061499, 2014). "The experimental results demonstrated a high Notch1 expression in lung adenocarcinoma and squamous cell carcinoma, while low Notch1 expression was observed in SCLC." (PMID 23420695, 2013). "NOTCH1 is reported as both a tumor suppressor and an oncogene across squamous cell carcinomas." (PMID 37444412, 2023).
squamous cell carcinoma (continued). "Specifically, NOTCH1 may play a dual role as either a tumor suppressor or (more rarely) as a protooncogene, specifically in squamous carcinomas." (PMID 33430387, 2021). "Additionally, signaling cross-talk in squamous cell carcinoma involving NOTCH1 with the transforming growth factor beta (TGF-β) pathway represses NOTCH3 through zinc finger E-box binding homeobox 1 (ZEB1) and promotes EMT and tumor initiation." (PMID 33322834, 2020). "Indeed, in squamous cell carcinoma, NOTCH1 induces the expression of Zinc finger E-box-binding homeobox 1 (ZEB1), a transcription factor that acts as a negative regulator of Notch3 gene expression." (PMID 32908186, 2020). "However, there is another report which demonstrated a divergent impact of Notch1 expression based on histological subtypes, adenocarcinoma and squamous cell carcinoma." (PMID 28060745, 2017). "Though not statistically significant in either lung adenocarcinoma or squamous cell carcinoma alone, higher NOTCH1 level predicted overall poorer patient survival, suggesting that targeting NOTCH1 may be useful for a subset of NSCLC patients." (PMID 26491213, 2015). "In esophagus, in vitro study in a commercial esophagus squamous cell carcinoma cell line with a pcNICD expression vector indicates that activated Notch1 signaling pathway gave rise to proliferation suppression of the cells, accompanied with a cell cycle inhibition at the G0/G1 phase and apoptosis." (PMID 23409141, 2013). "Although the function of Notch3 is highly indicated to squamous cell differentiation, studies of Notch1function in response to hypoxia in squamous cell carcinoma cell lines and large series of clinicopathological correlation of Notch1 in human squamous cell carcinomas are still missing." (PMID 23409141, 2013). "Given the overrepresentation of squamous cell carcinoma in our test set (68.29%), the prominence of NOTCH1 in our analysis may reflect squamous cell carcinoma-specific biological interactions or dependencies involving this gene, which merit further investigation." (PMID 41488620, 2025). "Although a subject of intense debate, these and many other observations point to the possibility that NOTCH1 may act as a tumor suppressor during the initiation of squamous carcinomas, but its tumor-promoting functions may prevail in later stages of cancer progression." (PMID 33430387, 2021). "Our results agree with those observed in squamous cell carcinomas, where RND3 depletion suppresses NOTCH1-mediated signaling." (PMID 38343633, 2024). "Previous results have shown that, in squamous cell carcinomas, RND3 was essential for the recruitment of intracellular domain of NOTCH1 to its target gene promoters by favoring NOTCH1 translocation to the nucleus." (PMID 38343633, 2024). "NOTCH1 and EGFR have been demonstrated to have antagonistic effects in skin cancer, where suppression of EGFR results in enhanced differentiation of squamous cell carcinoma cells and increased resistance to apoptosis." (PMID 36382054, 2022). "Recent research has shown that the NOTCH1 intracellular domain (N1ICD) and TGFβ cooperate to enhance the expression of SNAIL and ZEB1 in squamous cell carcinoma." (PMID 34944837, 2021). "In squamous cell carcinoma, USP28 is strongly expressed and stabilizes the essential squamous transcription factor ΔNp63, together with important oncogenic factors, such as NOTCH1, c-MYC and c-JUN." (PMID 34685632, 2021). "The EDF genes specific for the histology subtype also include TSHR, KEAP1, and EGFR in adenocarcinoma, and NOTCH1, PIK3CA in squamous cell carcinoma." (PMID 33078899, 2020). "In agreement with the luciferase assay, accumulation of NOTCH1 protein upon treatment with PLK1 inhibitors was observed in arsenite-untreated and -treated HaCaT cultures as well as in SCC022, a squamous cell carcinoma–derived cell line." (PMID 31597699, 2019).
squamous cell carcinoma (continued). "For instance, positive NOTCH1 staining was found in about half (43.9%) of the NSCLC tissues (n = 305, consisting of 210 squamous carcinomas and 95 adenocarcinomas), whereas only 15% of the normal lung tissues (n = 80) were positive for NOTCH1 staining." (PMID 26491213, 2015). "Recent research has suggested that after Notch‐1 activation, cells produce epithelial‐mesenchymal transition (EMT), which leads to the initiation of squamous cell carcinoma, which indicates that Notch‐1 signal can regulate the changes of cell morphology and movement." (PMID 39343985, 2025). "In contrast to NOTCH1, NOTCH3 limits EMT in squamous cell carcinoma." (PMID 33430387, 2021). "Yet, NOTCH1 can substitute a blockade on hypoxia and trigger EMT in squamous cell carcinomas (SCC)." (PMID 33430387, 2021). "In this manuscript, the authors reveal that Notch1 activation and EMT promote tumor initiation and cancer cell heterogeneity in squamous cell carcinoma, while the repression of Notch3 by ZEB1 limits Notch1-induced differentiation, permitting Notch1-mediated EMT." (PMID 29170450, 2017). "Although it was not an independent prognostic factor for squamous cell carcinoma, the combination of NOTCH1 and VEGF-A (vascular endothelial growth factor A) expression levels did predict worse patient survival (n = 164)." (PMID 26491213, 2015). "NOTCH1 expression level was found to be an independent prognostic factor that predicted worse survival of lung adenocarcinomas (n = 111), but not squamous cell carcinomas." (PMID 26491213, 2015). "Surprisingly, mice with activated KrasG12D and Notch1 but not Notch2 ablation developed skin papillomas progressing to squamous cell carcinoma providing evidence for Pdx1 expression in the skin." (PMID 21042537, 2010). "However, there was no statistical association between Notch1 expression and two main histological types of NSCLC: adenocarcinoma (ADC) and squamous cell carcinoma (SCC) (pooled OR = 0.96, 95%CI: 0.75-1.22, p = 0.068 and I2 = 42.1%)." (PMID 25996086, 2015).
osteosarcoma (51 papers, 2009 to 2026). A usually aggressive malignant bone-forming mesenchymal neoplasm, predominantly affecting adolescents and young adults. "In conclusion, our study showed that Notch1 activation could suppress cell proliferation by causing S phase arrest and induce apoptosis and autophagy in human osteosarcoma cells." (PMID 34495871, 2021). "We further revealed that changing the activity of Notch1 signaling pathway was able to affect the cell apoptosis to regulate the sensitivity of osteosarcoma to cisplatin, which might be mainly caused by the expression and/or activity changes of Caspase family proteins." (PMID 24894297, 2014). "Since Notch‐1 is a vital element of the pathophysiology of human osteosarcoma and actively participates in the process of cell survival, invasiveness, and metastasizing, the use of this factor as a therapeutic target becomes highly interesting." (PMID 41179371, 2025). "Human Deltex (DTX1) was also shown to regulate NOTCH1/HES1 signaling negatively in osteosarcoma cells." (PMID 38900140, 2024). "In conclusion, the abnormal activation of NOTCH1 signaling exerts a profound effect on the self-renewal of CSCs in osteosarcoma." (PMID 36975516, 2023). "This suppression subsequently activates the NOTCH1 and Hedgehog pathways, fueling osteosarcoma growth and metastasis." (PMID 38140058, 2023). "Activation of NOTCH1 signaling can also inhibit the apoptosis of osteosarcoma cells by downregulating p21 and Bax and upregulating BCL-2 and BCL-xL." (PMID 36975516, 2023). "A study found that inhibition of the Jag1/NOTCH1 pathway resulted in the arrest of the G1 phase of the cell cycle in osteosarcoma by reducing the expression of cyclin D1, cyclin E1, E2, and Skp2 and promoting the expression of p21." (PMID 36975516, 2023). "A study using NOTCH1 knockout mice reported a significant increase in the infiltration of M2-type TAMs in osteosarcoma tissues accompanied by decreased secretion of the Th1-type cytokines and increased secretion of the Th2-type cytokines." (PMID 36975516, 2023). "Exosomes from human umbilical vein endothelial cells promoted the self-renewal of CSCs in osteosarcoma by enhancing the expression of NOTCH1, Hes1, and Hey1 while blocking NOTCH signaling reversed the positive effect on the CSCs." (PMID 36975516, 2023). "A study found that the transcription of NOTCH1.Jag1 and target genes (Hes1 and Hey2) was upregulated in osteosarcoma specimens." (PMID 36975516, 2023). "The sensitivity of osteosarcoma Saos-2 cells with a high expression of NOTCH1 to cisplatin was significantly higher than that of MG63 cells with a low expression." (PMID 36975516, 2023). "A study found that inhibition of NOTCH1 signaling significantly restrained the growth of CSCs in osteosarcoma." (PMID 36975516, 2023). "On the contrary, another study reported that NOTCH1 signaling enhanced chemotherapy resistance by promoting Eph/ephrin reverse signal transduction in osteosarcoma U2OS, MG63, and 143B cells." (PMID 36975516, 2023). "In U2OS osteosarcoma cells, curcumin inhibits the expression of Notch-1 and matrix metalloproteases (MMP)-2, and -9." (PMID 35408894, 2022). "LIF promotes the stem cell properties of osteosarcoma through the NOTCH1 signaling pathway and enhances the growth and invasion of osteosarcoma by activating STAT3 signaling, while blocking STAT3 signaling can inhibit the development of osteosarcoma." (PMID 35740622, 2022). "By activating cell division cycle 20, Notch-1 increases the evolution of osteosarcoma to a malignant state." (PMID 36303551, 2022). "Diallyl trisulfide (DATS), a dietary bioactive compound derived from Allium vegetables, inhibited the expression of Notch-1, and Hes-1 in osteosarcoma cells." (PMID 35408894, 2022).